CGB5 (chorionic gonadotropin subunit beta 5)
Diseases named in the same sentence as CGB5 in open-access papers:
CGB5 is named in the same sentence as 19 diseases in open-access papers, as found by Europe PMC text mining. Sharing a sentence is not in itself a finding about the gene and the disease. The quoted sentences say what the papers report.
gastric cancer (7 papers, 2018 to 2025). A primary or metastatic malignant neoplasm involving the stomach. "Additionally, experimental studies were performed to examine the expression level of CGB5 in gastric cancer and to elucidate the potential mechanisms underlying its impacts on prognosis." (PMID 41048937, 2025). "Additionally, CGB5 is associated with specific immune sub-types in various cancers, including endometrial, testicular germ cell, and gastric adenocarcinoma, and closely linked to clinical features of gastric cancer patients." (PMID 41048937, 2025). "CGB5 is one of the key hCGβ encoding genes, which acts as a proangiogenic factor in some tumors, suggesting that CGB5 might also promote angiogenesis in gastric cancer." (PMID 32908579, 2020). "Immunohistochemical analysis revealed that CGB5 exhibited significantly increased expression in six tumor tissues, including liver, lung, and gastric cancers, compared to normal control tissues." (PMID 41048937, 2025). "First, we confirmed the up-regulation of CGB5 expression in gastric cancer cells through experimental validation." (PMID 41048937, 2025). "Compared to normal tissues, CGB5 is significantly up-regulated in six tumor types, such as liver, lung, and gastric cancers." (PMID 41048937, 2025). "Our results demonstrated that CGB5 facilitates gastric cancer progression via multiple pathways, with significant enrichment observed in the Wnt signaling pathway through both GO and KEGG analyses." (PMID 41048937, 2025). "In this study, we confirmed the robust expression of CGB5 in gastric cancer cells and further investigated its mechanism of action." (PMID 41048937, 2025). "Previous studies have explored the role of CGB5 in gastric cancer, primarily focusing on gene set analyses while offering limited insight into its underlying mechanisms." (PMID 41048937, 2025). "Previous studies have provided evidence to supporting the notion that CGB5 plays a critical role in gastric cancer, ovarian cancer, and squamous lung cancer, and is closely associated with patient prognosis." (PMID 41048937, 2025). "In coherence with our study, chorionic gonadotropin subunit beta 5 (CGB5) – a protein-encoding gene primarily associated with invasive mole and ectopic pregnancy – has previously been identified as a biomarker in gastric cancer." (PMID 36389725, 2022). "This is consistent with the findings of our study, in which CGB5 was revealed as a key gene for predicting the prognosis of patients with gastric cancer." (PMID 34222004, 2021). "We analyzed all pathological tissue sections and found that the expression of CGB5 was significantly higher in gastric cancer than in paraneoplastic tissue (Figures 15A1, B2)." (PMID 34222004, 2021). "In this study, using data from the International Cancer Genome Consortium (ICGC) and the Cancer Genome Atlas (TCGA)‐stomach adenocarcinoma (STAD), we assessed the independent prognostic value of CGB5 expression in patients with primary gastric cancer (GC)." (PMID 29473345, 2018). "Furthermore, CGB5 expression in gastric cancer cells was experimentally detected, and the potential mechanisms underlying its impact on prognosis were elucidated." (PMID 41048937, 2025). "Furthermore, GSEA analysis suggests that CGB5 may promote gastric cancer progression by modulating the immune microenvironment, underscoring the pivotal role of immune infiltration in gastric cancer, findings that are consistent with prior research." (PMID 41048937, 2025). "The CGB5, MKNK2, and PAPPA2 genes may serve as important biomarkers for predicting the prognosis of gastric cancer." (PMID 34222004, 2021). "CGB5, MKNK2, and PAPPA2 may be used as novel prognostic biomarkers for gastric cancer." (PMID 34222004, 2021).
ovarian carcinoma (5 papers, 2018 to 2025). A malignant neoplasm originating from the surface ovarian epithelium. "Existing studies substantiate the notion that CGB5 plays a pivotal role in various cancers, including gastric and ovarian cancers, and is strongly associated with patient prognosis." (PMID 41048937, 2025). "Overexpression of CGB5 in ovarian cancer cells results in increased receptor expression, and interaction between the two accelerates tumor growth and the development of ovarian cancer." (PMID 38228846, 2024). "It is reported that in ovarian cancer, CGB5 may activate the LHR signaling pathway and thus appears to promote tumor growth and the formation of angiogenic mimics." (PMID 34222004, 2021). "Additionally, overexpression of CGB5 induced the growth of ovarian cancer cells in a xenograft murine model, as well as VM." (PMID 31612116, 2019).
bladder cancers (2 papers, 2017 to 2020). "Analysis of TCGA data sets by Oncomine and cBioPortal, showed that pancreas/breast/bladder cancers present significant amplification of CGB5." (PMID 28869585, 2017).
breast carcinoma (1 paper, 2017). "Further, human breast cancer tissue samples (n=3831) were analyzed using three cBioportal TCGA data sets, in which the expression levels of CGB5, CGB7 and BRCA1 were available." (PMID 28869585, 2017).
breast invasive carcinoma (1 paper, 2017). "The expression levels of CGB5, CGB7 and BRCA1 from breast invasive carcinoma study (TCGA, Cell 2015) is represented as heat map." (PMID 28869585, 2017).
cervical squamous cell carcinoma (1 paper, 2021). A squamous cell carcinoma arising from the cervical epithelium. "Recent studies have demonstrated that CGB5, a member of the CGB family, may have an important role in cervical squamous cell carcinoma, pancreatic adenocarcinoma, and rectal adenocarcinoma." (PMID 34222004, 2021).
COVID-19 (1 paper, 2024). A disease caused by infection with severe acute respiratory syndrome coronavirus 2. "Chorionic gonadotropin subunits CGB5 and GCB8 both exhibited significant downregulation in the COVID-19-positive women." (PMID 38338886, 2024).
gastric tumor (1 paper, 2023). "The results obtained from reverse transcription-quantitative polymerase chain reaction (RT-qPCR) and immunohistochemical indicated that the expression levels of CGB5, UPK1B, and PI15 were downregulated in gastric tumor cells, while DNAAF3 was upregulated." (PMID 37711621, 2023).
preeclampsia (1 paper, 2024). Preeclampsia is a hypertensive disorder of pregnancy that is characterized by new-onset hypertension with proteinuria presenting after 20 weeks of gestation, and depending on mild or severe forms may initially present with severe headache, visual disturbances, and hyperreflexia. "Previous research delineated a significant downregulation of Metastasis-associated protein 3 (MTA3) in the placenta affected by preeclampsia, in contrast to the upregulation of both CGB5 and Snail." (PMID 39544937, 2024). "The biomarkers CGB5, LEP, LRRC1, PAPPA2, and SLC20A1 offer varying prospects for predicting preeclampsia." (PMID 39544937, 2024).
Primary immunodeficiency (1 paper, 2025). "The results demonstrate that CGB5 is predominantly associated with immune-related pathways, including “Primary immunodeficiency,” “CD8 TCR signaling pathway,” and “PD-1 checkpoint signaling”." (PMID 41048937, 2025).
renal carcinoma (1 paper, 2010). A carcinoma arising from the epithelium of the renal parenchyma or the renal pelvis. "At the genomic level, activation of transcription of CGB, CGB5 and CGB8 genes has been associated with malignant transformation of non-trophoblastic cells (breast, bladder, prostate, thyroid, testis and renal cancer)." (PMID 20488225, 2010).
trophoblastic neoplasm (1 paper, 2018). A gestational or non-gestational neoplasm composed of neoplastic trophoblastic cells. "The human CGB5 gene encodes chorionic gonadotropin (hCG)β 5, which is aberrantly expressed in trophoblastic neoplasm and in some non‐trophoblastic neoplasms." (PMID 29473345, 2018).
urothelial carcinoma (1 paper, 2025). A malignant neoplasm derived from the transitional epithelium of the urinary tract (urinary bladder, ureter, urethra, or renal pelvis). "We first wondered how frequently CGB7 is coexpressed with CGB3, CGB5, CGB8, and CGA in urothelial carcinoma." (PMID 40501795, 2025). "Further evaluation of expression of these genes in the TCGA urothelial carcinoma cohort revealed that while tumors tend to co-express CGB3, CGB5, and CGB8, CGB7-expressing tumors cluster independently, suggesting that CGB7 is less frequently co-expressed with CGB3, CGB5, and CGB8." (PMID 40501795, 2025).
tumor (9 papers, 2021 to 2025). "This study demonstrates that CGB5 expression is closely associated with immune cell infiltration across cancer types, showing significant variation in infiltration patterns among tumor types." (PMID 41048937, 2025). "Sex-stratified analyses further confirmed sex-independent associations between CGB5 overexpression and adverse outcomes, highlighting its tumor-specific functional profile and clinical translational potential." (PMID 41048937, 2025). "Specifically, the expression level of CGB5 appears to directly affect the distribution and functional state of immune cells within the tumor microenvironment, offering valuable clues for elucidating the mechanisms underlying tumor immune evasion." (PMID 41048937, 2025). "From a clinical standpoint, CGB5 exerts dual functions—driving intrinsic tumor aggressiveness while profoundly reshaping the immune microenvironment–thereby serving as both a prognostic biomarker and a compelling therapeutic target." (PMID 41048937, 2025). "The results demonstrated that CGB5 exhibited diverse expression patterns in most tumor types, with differential expression observed, including high expression, no significant differential expression, or low expression." (PMID 41048937, 2025). "CGB5-expressing tumor cells convert conventional CD4+ T cells into Tregs by up-regulating the immunosuppressive cytokines TGF-β and IL-10, together with the transcription factor FOXP3." (PMID 41048937, 2025). "Extensive studies indicate that CGB5 expression in tumor tissues may facilitate tumorigenesis and progression by modulating the tumor immune microenvironment." (PMID 41048937, 2025). "However, in this study, high CGB5 expression exhibited an inverse correlation with immune cell infiltration in different tumor types." (PMID 41048937, 2025). "We first tested whether the associations between CGB7 and CD8+ T cell infiltration and tumor subtype are upheld independently of CGB3, CGB5, and CGB8 expression." (PMID 40501795, 2025). "Second, although CGB5 expression was confirmed in GC cell lines in this study, functional validation and further investigations in additional tumor types(such as PAAD) demand comprehensive in vitro and in vivo experiments utilizing relevant cancer cell lines and/or animal models." (PMID 41048937, 2025). "Vaccination protocols or antibody-based neutralization of hCGβ markedly attenuated tumor growth in experimental models, indicating that disruption of CGB5-dependent pathways can re-invigorate antitumor immunity and enhance responsiveness to immune-checkpoint blockade." (PMID 41048937, 2025). "Additionally, the investigation of the expression of four signature genes in the tumor immune microenvironment through single-cell sequencing analysis confirmed the presence of CGB5, PI15, UPK1B, and DNAAF3 in the T cell cluster." (PMID 37711621, 2023). "Additionally, the expression of CGB5 was analyzed in 23 tumor types with paired samples in TCGA." (PMID 41048937, 2025). "Mechanistic studies further demonstrate that exposing tumor cells to hCG augments FOXP3 expression and increases Treg differentiation, indicating that CGB5-mediated signaling is a key driver of the immune-evasion phenotype." (PMID 41048937, 2025). "Five genes were subsequently selected by LASSO regression; CGB5, THPO, and PDGFRB were upregulated in the tumor tissue, while SLC10A2 and APOD were downregulated." (PMID 38228846, 2024). "From the RT-qPCR and immunohistochemical, the expression of DNAAF3 was higher in tumor and the expression of PI15, UPK1B, and CGB5 was lower in tumor." (PMID 37711621, 2023). "Specifically, CGB5 disrupts canonical TGF-β signaling, thereby driving fibroblasts to acquire a CAF phenotype characterized by robust secretion of ECM proteins and pro-inflammatory cytokines, ultimately remodeling the ECM and facilitating tumor invasion." (PMID 41048937, 2025).
tumor (continued). "From these findings, it is evident that CGB5 expression exhibited the strongest positive correlation with the stromal content and immune grade of tumor samples, while displaying a negative correlation with the immunological index." (PMID 41048937, 2025). "Mechanistically, CGB5 over-expression likely influences tumor progression not only through modulation of immune infiltration but also via interactions with multiple signaling pathways." (PMID 41048937, 2025).
cancer (8 papers, 2019 to 2025). A tumor composed of atypical neoplastic, often pleomorphic cells that invade other tissues. "Compared with T cells, CGB5 expression exhibited a stronger positive correlation with the infiltration of B cells and cancer-associated fibroblasts (CAFs)." (PMID 41048937, 2025). "This would specifically interrogate CG5′s functional modulation within cancer-associated fibroblasts and T-cell subpopulations, thereby advancing mechanistic insights for developing precision immunotherapies targeting CGB5." (PMID 41048937, 2025). "The findings revealed that CGB5 expression was correlated with DSS in PAAD and STAD, with high CGB5 expression being associated with poorer DSS in these cancers." (PMID 41048937, 2025). "The results demonstrated that CGB5 expression exhibits a significant association across various cancer types." (PMID 41048937, 2025). "In this study, we investigated the gene mutations and CNVs of the CGB5 gene across pan-cancer types." (PMID 41048937, 2025). "To summarize, CGB5 expression was significantly up-regulated across a range of malignancies and exhibited a robust association with the prognoses of cancer patients, specifically in malignancies like GC and PAAD." (PMID 41048937, 2025). "Notably, CGB5 exhibits strong associations with immune cell infiltration, with distinct patterns and magnitudes observed in specific cancers." (PMID 41048937, 2025). "Through comprehensive analysis of gene mutations, CNVs, and DNA methylation status, we can more comprehensively reveal the role of the CGB5 gene in cancer and its potential biological significance." (PMID 41048937, 2025). "Our pan-cancer analysis demonstrates that aberrant CGB5 expression significantly correlates with poor prognosis across multiple cancer types, specifically in malignancies like GC and PAAD, potentially driven by genetic mutations, DNA methylation, and CNAs." (PMID 41048937, 2025). "The correlations between B cells, cancer-associated fibroblasts (CAFs), CD8+ T cells, and CGB5 expression were comprehensively visualized in the heatmap." (PMID 41048937, 2025). "To investigate the mRNA expression levels of the CGB5 gene across various cancer types, we performed an analysis using TCGA harmonization data obtained from UCSC." (PMID 41048937, 2025). "In our study, we observed a robust correlation between CGB5 expression across various cancer types and immune cell infiltration." (PMID 41048937, 2025). "Subsequently, we conducted an analysis to evaluate the influence of CGB5 expression on immunological and molecular subgroups across pan-cancer types." (PMID 41048937, 2025). "In the present study, a comprehensive analysis of the genomics, transcriptomics, epigenetics, immune microenvironment, and clinical and prognostic significance of CGB5 was conducted across various cancer types." (PMID 41048937, 2025). "We utilized diverse algorithms to investigate the potential correlation between CGB5 expression and the infiltration levels of various immune cell types across pan-cancer datasets." (PMID 41048937, 2025). "The results indicated a significant association between CGB5 expression and PFI in PAAD and STAD, where elevated CGB5 expression was associated with poorer PFI in these cancer types." (PMID 41048937, 2025). "Overall, these findings indicate CGB5 as a promising biomarker for pan-cancer diagnosis and prognosis." (PMID 41048937, 2025). "CGB5 is significantly up-regulated in various malignancies and strongly correlates with cancer patient prognoses, specifically in malignancies like GC and PAAD." (PMID 41048937, 2025). "Chorionic gonadotropin beta polypeptide 5 (CGB5) can accelerate cancer growth and vasculogenic mimicry formation by activating the LHR signaling pathway." (PMID 39749345, 2024). "Analysis of mRNA derived from placentas and cancer tissues pointed to a twenty fold higher transcriptional activity of CGB5 compared to CGB3 or CGB8." (PMID 31362717, 2019).
cancer (continued). "The results of pan-cancer analysis indicate that CGB5 exhibits significant prognostic value in GC." (PMID 41048937, 2025). "Furthermore, we assessed the correlation between CGB5 expression and immune cell infiltration across pan-cancer datasets using multiple algorithms, including TIMER, EPIC, QUANTISEQ, XCELL, CIBERSORT, MCPCOUNTER, IPS, and Quantiseq." (PMID 41048937, 2025). "Additionally, we observed significant expression of CLDN6, CES1, SOST, SPRR2A, MYBPH, CGB5, and KRT1 in the high-risk group, suggesting their potential involvement as cancer-promoting genes in BLCA development." (PMID 37780567, 2023). "Furthermore, in the high-risk group, AFP, CST6, CGB5, and ELANE were significantly expressed, indicating their potential roles as cancer-promoting genes in the development of STAD." (PMID 37377916, 2023). "CGB, also known as CGB5, plays an important role in cancer growth, invasion, and metastasis." (PMID 35627105, 2022). "Furthermore, we evaluated the protein expression levels of CGB5 across multiple cancer types." (PMID 41048937, 2025). "Comparing expression of each CGB gene in tumor and matched normal peritumoral tissues across these datasets elucidated extensive cancer-specific expression of CGB3, CGB5, CGB7, and CGB8 across cancer types." (PMID 40501795, 2025). "However, to date, there have been no comprehensive reports investigating the role of CGB5 in pan-cancer analysis." (PMID 41048937, 2025). "However, to date, there have been no comprehensive reports investigating the role of CGB5 across pan-cancer." (PMID 41048937, 2025). "Moreover, to validate CGB5′s role in immunotherapy response, future experiments could employ CRISPR/Cas9-mediated CGB5 knockout in cancer cell lines to evaluate changes in immune cell infiltration and response to ICIs." (PMID 41048937, 2025). "Numerous studies have demonstrated that beta-hCG-encoding genes are expressed in various cancers, but expression of these genes (CGB3, CGB5, CGB7, and CGB8) across diverse cancers has not been systematically evaluated." (PMID 40501795, 2025).
CGB5 also shares sentences with these, for which no sentence is quoted: gastric adenocarcinoma (2 papers); invasive mole (1); osteosarcoma (1); rectal adenocarcinoma (1).